EMB (embigin)
Diseases named in the same sentence as EMB in open-access papers (continued):
Sharing a sentence is not in itself a finding about the gene and the disease.
schizophrenia (1 paper, 2020). A major psychotic disorder characterized by abnormalities in the perception or expression of reality. "The SNP, rs3933097 located in 3′-UTR of EMB gene, is significantly associated with schizophrenia both in allelic and genotypic distributions in our study." (PMID 32213169, 2020). "In our results, rs3933097 in 3′-UTR of EMB gene is significantly associated with schizophrenia and Several miRNAs, hsa-miR-508-3p, hsa-miR-182, hsa-miR-335 and hsa-miR-580, are predicted to bind with the seed region containing rs3933097 by SNPinfo Web Server." (PMID 32213169, 2020). "Our research provides additional evidence that EMB gene is a susceptibility gene for schizophrenia, but further functional validations are considered to be necessary for understanding EMB correlated with the etiology in schizophrenia." (PMID 32213169, 2020). "Overall, our results provide evidence that EMB gene is a susceptibility gene for schizophrenia which is consistent with the prediction of recent GWAS." (PMID 32213169, 2020). "Sequencing the exons and UTR of EMB gene can help us to find out the causal variants of EMB gene for schizophrenia, further understand the role of EMB gene in schizophrenia, and lay a foundation for us to study the pathogenesis of schizophrenia." (PMID 32213169, 2020). "The research also suggested that the EMB gene is one of the prioritized candidate genes, which had more than one line of supporting evidence, implicated in schizophrenia." (PMID 32213169, 2020). "Our research first presented a comprehensive mutation spectrum of exons and un-translated region in EMB gene for schizophrenia and provided additional evidence of EMB gene being a susceptibility gene for schizophrenia." (PMID 32213169, 2020). "We identify two novel nonsynonymous mutations in EMB gene and first report the SNP, rs3933097, located in the 3′-UTR of EMB gene is significantly associated with schizophrenia." (PMID 32213169, 2020). "The recent GWAS newly reported rs10940346 (P = 1.11 × 10− 8, odds ratio (OR) = 0.949, standard error (SE) = 0.009) locus near EMB gene is significantly associated with schizophrenia and EMB gene was reported to be the notable gene." (PMID 32213169, 2020). "Our result reveals rs3933097 in 3′-UTR of EMB gene is significantly associated with schizophrenia by which the mRNA expression level of EMB gene might be regulated and affected." (PMID 32213169, 2020). "In addition, a common variant, rs3933097 located in 3′-UTR of EMB gene, achieved allelic and genotypic significance with schizophrenia (Pallele = 3.82 × 10− 6, Pgenotype = 3.18 × 10− 5)." (PMID 32213169, 2020). "Moreover, the latest GWAS in schizophrenia also suggested that EMB gene is one of the potentially causal genes for schizophrenia." (PMID 32213169, 2020). "The results of latest GWAS in schizophrenia showed that EMB gene is one of the potentially causal genes at 33 genome-wide significant loci (rs77853293, P = 1.77 × 10− 8, odds ratio (OR) for allele “C” =1.056, standard error (SE) = 0.010, gene tagged: EMB, PSMR = 1.12 × 10− 6)." (PMID 32213169, 2020). "Furthermore, our study confirms the previous GWAS result and suggests that the polymorphism of 3′-UTR sequence of EMB gene may be involved in the pathogenesis of schizophrenia." (PMID 32213169, 2020). "In order to scan pathogenic mutation sites related to schizophrenia in EMB gene, next-generation sequencing for the UTR and all exons of EMB gene in 1803 cases and 997 healthy controls were performed via the multiplex PCR technology and Illumina platform." (PMID 32213169, 2020). "As a member of the IgSF, the EMB gene also plays an important role in embryonic development, which implies that there is a connection between the EMB gene and schizophrenia." (PMID 32213169, 2020).
schizophrenia (continued). "We discovered a SNP locus located in 3′-UTR of EMB gene is significantly associated with schizophrenia, but further functional validations are necessary for understanding the etiology correlated with 3′-UTR of EMB in schizophrenia." (PMID 32213169, 2020). "Recent genome-wide association study showed rs10940346 locus near EMB gene was significantly associated with schizophrenia and suggested that EMB gene is one of the potentially causal genes for schizophrenia, but no causal variant has been identified." (PMID 32213169, 2020). "Although EMB gene was suggested to be one of the potentially causal genes for schizophrenia, no real causal variant on EMB gene has been identified yet." (PMID 32213169, 2020).
tumor (62 papers, 2010 to 2026). "Finally, online data analysis showed that embigin expression is low in basal-like tumors and loss/low of embigin significantly correlates with increased tumor recurrence in patients, particularly those with basal-like cancers." (PMID 26090721, 2015). "In our study, we found that the HP infection score in the tumor group was notably higher than that in the normal group and screened five key prognostic genes (CTLA4, CPVL, EMB, CXCR4, and FAM241A) from the HP infection–related DEGs in STAD to establish a riskscore model." (PMID 39886652, 2025).
cancer (16 papers, 2011 to 2025). A tumor composed of atypical neoplastic, often pleomorphic cells that invade other tissues. "By this approach, we found that highest number of genes altered (up and down) in embigin overexpression are associated with cancer diseases." (PMID 30041429, 2018). "Due to the similarity of embigin to SSSRs, we focused on S100 proteins, which have been reported to be associated with cancer progression." (PMID 30041429, 2018). "EMB (Embigin) encodes a transmembrane protein belonging to the immunoglobulin superfamily that has been identified as a biomarker for cancer progression." (PMID 27929140, 2016). "Low embigin expression was significantly associated with decreased survival rate in patients with basal-like cancers (logrank p = 0.0005)." (PMID 26090721, 2015). "Carcinoma patients showed a dramatic increase in the expression of MAPK8IP2 in CARD11+ carcinoma patients alongside other cancer-related genes, including EMB, EPHB6, and CPEB4." (PMID 39408697, 2024). "In this study, we tried to identify a novel ligand of embigin and to determine the importance of embigin in cancer progression." (PMID 30041429, 2018). "As a transcription factor, HOXC8 is able to regulate and coordinate multiplevital genes (e.g. Mgl1, Embigin, Meis1, and Fyn) involved in cancer development and progression." (PMID 32922885, 2018). "Taken together, our results indicate that embigin mediates multiple cancer cell behaviors including migration, invasion, growth, colony formation, and spheroid formation." (PMID 30041429, 2018). "In order to understand the importance of embigin in cancer progression, we determined embigin mRNA and protein expression levels in various cancer cell lines by quantitative PCR and WB analysis." (PMID 30041429, 2018). "The transmembrane glycoprotein embigin (EMB) belongs to the immunoglobulin superfamily (IgSF) and a number of IgSF members have been identified as biomarkers for cancer progression." (PMID 26090721, 2015). "Interestingly, ABCA1 and ETV1 are upregulated genes by embigin overexpression in both cancer and metabolic disease cluster." (PMID 30041429, 2018). "Accordingly, we first evaluated the effect of the S100A4-embigin axis on cancer cell migration." (PMID 30041429, 2018). "ABCA1, an ABC transporter, but not ABCB1, ABCC1 or ABCC2, might be involved in the anti-cancer drug resistance observed in DU145 cells stably overexpressing embigin." (PMID 30041429, 2018). "However, very little is known about the regulation of embigin expression and its roles in cancer development." (PMID 26090721, 2015). "However, the biological functions of embigin in cancer remain elusive." (PMID 30041429, 2018). "The remaining nine surface proteins identified solely (ANTXR1, AG1, DCBLD2, EFNB1, EMB, OSMR, SLC1A5) or found upregulated (ATP1B3 and ITGB1) on the MCF10A surface had no direct association with embryonic development signaling in the context of KRas mutant signaling in cancer cell lines." (PMID 27894102, 2016). "Additional genes upregulated in carcinoma patients as a result of CARD11 overexpression included MTMR2, EMB, EPHB6, and CPEB4, which are related to various cancer-related processes." (PMID 39408697, 2024). "We found by a pull-down assay that embigin is a novel receptor for S100A4, which is one of the vital cancer microenvironment milleu." (PMID 30041429, 2018). "In this study, we investigated the importance of embigin and S100A4 in cancer progression." (PMID 30041429, 2018). "As well as its obscure role in cancer, a ligand for embigin has not been identified." (PMID 30041429, 2018). "However, it is still not known how embigin regulates these cancer-related molecules and whether embigin-mediated AMPK/mTORC1 and NF-κB pathways are required for the regulation of these molecules." (PMID 30041429, 2018).
EMB also shares sentences with these, for which no sentence is quoted: infection (36 papers); sporotrichosis (14); colon carcinoma (6); HIV-1 infection (4); lupus (4); colorectal cancer (3); melanoma (2); B cell lymphoma (1); co-infection (1); colorectal tumor (1); deafness (1); diabetes (1); metabolic disease (1); mycosis (1); Nephropathy (1); pancreatic adenocarcinoma (1); pancreatic ductal adenocarcinoma (1); Splenomegaly (1); Stroke (1).